MMP9 (matrix metallopeptidase 9)
Diseases named in the same sentence as MMP9 in open-access papers (continued):
Sharing a sentence is not in itself a finding about the gene and the disease.
ovarian tumor (continued). "By univariate analysis, high levels of MMP-2, MMP-9, MT1-MMP and TIMP-2, were detected by immunohistochemistry and/or mRNA in situ hybridization in tumor cells from peritoneal or pleural effusions, metastatic lesions and primary ovarian tumors." (PMID 22200690, 2012). "As a matter of fact, there is a close relationship between matrix metalloproteinases (MMPs) and VEGF in tumor progression, of which MMP-9 induces the release of biologically active VEGF in the culture of ovarian tumor cells and in ascites of ovarian tumor-bearing mice." (PMID 22992293, 2012). "MMP-9 co-upregulation was also observed in our study, which is in agreement with the finding that MMP-9 (and MMP-14) mRNA levels are selectively increased in response to EGFR activity in ovarian tumor cells." (PMID 18211683, 2008). "In the ovarian tumors from obese and non-obese KpB mice, treatment with celecoxib as compared to control resulted in decreased proliferation, increased apoptosis and reduced COX-2 and MMP9 protein expression, as assessed by immunohistochemistry." (PMID 27074576, 2016).
acute respiratory distress syndrome (24 papers, 2010 to 2025). Progressive and life-threatening pulmonary distress in the absence of an underlying pulmonary condition, usually following major trauma or surgery. "Lower MMP‐9 gene expression with LF‐PSV than with LF‐PCV has already been described in a similar model of acute respiratory distress syndrome receiving approximately 10 ml/kg/h of fluids, a difference not observed under a CF strategy." (PMID 36065867, 2022). "Moreover, MMPs are involved in tissue repair, as MMP7 and MMP9 have been reported to participate in epithelial tissue repair after damage caused by acute respiratory distress syndrome (ARDS)." (PMID 33271804, 2020). "Two studies identified elevated MMP-9 levels in the lungs of newborns with acute respiratory distress syndrome." (PMID 20205825, 2010). "MMP-2 and MMP-9 have been found to play an important role in ALI, acute respiratory distress syndrome (ARDS), and pulmonary fibrosis." (PMID 35872761, 2022). "Plasma MMP‐9 activity has further been described as potentially predictive for lung injury and the development of ARDS (acute respiratory distress syndrome) in critically ill patients." (PMID 31932967, 2021). "Notably, circulating MMP9 level has been reported as a biomarker for severe CAP, COVID-19, ventilator-associated pneumonia and acute respiratory distress syndrome (ARDS)." (PMID 38166679, 2024). "A recent study showed one week after admission, obese-diabetic patients with acute respiratory distress syndrome (ARDS) demonstrated notably elevated levels of MMP7 and MMP9 in their serum compared to non-ARDS patients, indicating increased activation of macrophages." (PMID 38803919, 2024).
edema (24 papers, 2012 to 2025). An abnormal accumulation of fluid beneath the skin, or in one or more cavities of the body. "In the study of patients and animal models, MMP‐9 caused brain edema after degradation of extracellular matrix protein and destruction of tight junctions (Hayman, Wessell, Gerzanich, Sheth, & Simard, 2017)." (PMID 32533644, 2020). "MMP9 destroyed the integrity of BBB, thereby causing cerebral hemorrhage and cerebral edema, and had certain toxic and side effects on neurons." (PMID 34224319, 2021). "This suggests that MMP‐9 has a close correlation with ischemic brain injury and secondary cerebral edema." (PMID 31566928, 2019). "No studies reported the association between MMP-9 rs3918242 polymorphism and brain edema or functional outcome after acute stroke." (PMID 33329294, 2020). "Similarly, our previous studies demonstrated that mRNA levels of MMP-9 increased markedly in the brain at the early stage of brain edema induced by 1,2-DCE in mice." (PMID 28769771, 2017). "Studies have highlighted the critical role of S1P2 in ischemia-reperfusion injury, confirming that genetic deletion or inhibition of S1P2 could block the development of hemorrhagic transformation and cerebral edema by inhibiting the matrix metalloproteinase-9 (MMP-9) activation in endothelial cells." (PMID 32580348, 2020). "Our study showed that early relief of severe bilateral carotid stenosis could lead to brain edema and elevation of BBB permeability, which was associated closely with increased activity and expression in MMP-9 and decreased quantity in tight junction proteins claudin-5 and occludin." (PMID 23469092, 2013). "MMP9-mediated sRAGE production inhibited the RAGE/NF-κB activation and consequently reduced the severity of pulmonary edema, inflammation, and oxidative stress." (PMID 35875560, 2022). "In summary, administering ectogenic PROG attenuates BBB damage and cerebral edema in HIBD neonatal rats by downregulating the expression of AQP-4 and MMP-9 in the brain cortex." (PMID 23935758, 2013). "Our previous research demonstrated that, following brain ischemic injury, picroside II can remove free radicals, has antioxidant properties, decreases MMP-9 expression and inhibits the toll-like receptor 4 and nuclear factor kappa B (TLR4-NFκB) signaling pathways to relieve cerebral edema." (PMID 25927985, 2015).
pneumonia (24 papers, 2008 to 2025). An acute, acute and chronic, or chronic inflammation focally or diffusely affecting the lung parenchyma, caused by an infection in one or both of the lungs (by bacteria, viruses, fungi, or mycoplasma.). "To explore the association between MMP9 polymorphism and the severe pneumonia subtype, we further divided our cohort into two subgroups: the primary diagnosis as severe pneumonia (n = 719) and the secondary diagnosis as severe pneumonia (n = 315)." (PMID 38166679, 2024). "Here we assemble a case–control cohort to study the association of genetic variants in MMP9 gene with severe childhood pneumonia susceptibility in a Southern Chinese population (1034 cases and 8426 controls)." (PMID 38166679, 2024). "Nevertheless, this study indicates that the polymorphisms in MMP9 are associated with the susceptibility to severe pneumonia in Southern Chinese children." (PMID 38166679, 2024). "A significant association between the respiratory microbiome and the MMP9 gene expression in the lung has previously been observed in pneumonia patients." (PMID 36232913, 2022). "In summary, our findings suggest that MMP9 is a novel predisposing gene for childhood pneumonia." (PMID 38166679, 2024). "However, the associations between MMP9 polymorphism and severe childhood pneumonia need further elucidation." (PMID 38166679, 2024). "In summary, MMP9 is associated with inflammatory diseases and is a biomarker for severe pneumonia." (PMID 38166679, 2024). "Taken together with our regulatory results, MMP9 SNPs may contribute to severe pneumonia susceptibility through regulatory properties which may impact MMP9 translational efficiency and protein level." (PMID 38166679, 2024). "Our results suggest epistatic association of MMP9 rs3918262 SNPs and severe childhood pneumonia." (PMID 38166679, 2024). "Finally, we demonstrated that protein levels of MMP9 were significantly increased in the BAL of patient with severe pneumonia, suggesting that MMP9 polymorphism may associated with the expression levels of MMP9 in severe pneumonia." (PMID 38166679, 2024). "The correlation between MMP9 and the risk of severe childhood pneumonia remains unclear." (PMID 38166679, 2024). "Consistent with the decrease in sRAGE in patients with pneumonia, decreased MMP9 levels were observed in pneumonia patients." (PMID 35875560, 2022). "We also found that MMP9 was significantly lower in patients with pneumonia, and it was positively correlated with sRAGE levels over 7 days after disease onset." (PMID 35875560, 2022). "MMP-8 and MMP-9 levels are increased in patients with pneumonia, and this increase in lung tissue induces neutrophil influx, thereby contributing to the elimination of infectious agents." (PMID 36142454, 2022). "Dementia patients have a 2-fold increased mortality rate from pneumonia, and pneumonia patients have elevated MMP-9 levels in their serum, which is known to be linked to BBB breakdown." (PMID 35517047, 2022). "The increase in TBB permeability by MMPs, including MMP-9, is thought to affect two aspects of inflammatory cell influx and pathogen dissemination in the pathology of pneumonia." (PMID 36142454, 2022). "In particular, high circulating levels of MMP8 and MMP9 were found in patients affected by inflammatory conditions, such as pancreatitis and pneumonia." (PMID 23442769, 2013). "Furthermore, MMP9 concentrations were significantly up-regulated in the bronchoalveolar lavages (BALs) of children with severe pneumonia." (PMID 38166679, 2024). "Meanwhile, the results of molecular docking also exposed the active ingredients of YPFG could tack a part in modulating the progression of pneumonia via MMP9, CCL2, IL-1B, IL-6, CXCL8, and TNF." (PMID 36285159, 2022). "While the biological role of ZmpB remains unknown, ZmpC has been demonstrated to cleave the matrix metalloproteinase MMP-9 and contribute to streptococcal virulence in experimentally induced pneumonia, but the mechanism of its action remains unclear." (PMID 22412870, 2012).
pneumonia (continued). "Consistent with the low sRAGE levels in pneumonia patients, MMP9 levels in patients with pneumonia were lower than those in patients without pneumonia." (PMID 35875560, 2022). "Finally, we measure the MMP9 protein levels in the BAL of children with severe or non-severe pneumonia." (PMID 38166679, 2024).
prostate tumor (24 papers, 2008 to 2025). "High expression and secretion of MMP-2 and MMP-9 have been associated with increased prostatic tumor invasion, an important phenomenon for subsequent tumor metastasis." (PMID 38137922, 2023). "A previous study demonstrated that TIMP-3 deficient mice promote prostate tumor growth, cell proliferation index, micro-vessel density, invasive capacity and the expression of MMP-9." (PMID 33730072, 2021). "In response to Lrp5-overexpressing MSC CM, TRAMP prostate tumor cells also reduced EdU-based proliferation, transwell-based invasion, downregulated tumorigenic genes such as Lrp5, Runx2, MMP9 and Snail." (PMID 33859739, 2021). "sTβRIII can also suppress the tumor formation and reduce lung metastasis via by binding TGF-β and inhibition of angiogenesis, and inhibit prostate tumor proliferation and angiogenesis through decreasing MMP-9 expression." (PMID 29796175, 2018). "Since SPDEF inhibits cell migration, at least in part, through MMP9 and MM13, increased expression of these MMP genes can contribute to Foxm1-mediated rescue of cell migration in SPDEF-deficient prostate tumor cells." (PMID 25254494, 2014). "CXCL8 interaction with the chemokine receptor CXCR2 induces gelatinase B/MMP-9 release from neutrophils, and activation of the chemokine receptor CXCR4 up-regulates gelatinase B/MMP-9 expression in prostate tumour cells, promoting invasion and metastasis." (PMID 24473089, 2014). "Rao and colleagues have demonstrated that downregulation of cathepsin B and MMP9 more effectively reduces invasion of prostate tumor cells in vitro and tumor growth in vivo than downregulation of either cathepsin B or MMP9." (PMID 22093547, 2011). "Moreover, the mRNA expression levels of MMP9 in the mouse prostate tumor were significantly lower in the FABP4−/− TRAMP-HF group than in the TRAMP-HF group." (PMID 41226657, 2025). "In addition, the mRNA expression levels of MMP9 in the mouse prostate tumor (20, 24, and 30 weeks of age) were significantly lower in FABP4−/− TRAMP-HF than in TRAMP-HF mice." (PMID 41226657, 2025). "Their expression in prostate tumors is related with disease progression and metastasis, whereas MMP9 was shown to increase growth factors bioavailability and to elicit epithelial-to-mesenchymal transition in tumor cells, therefore promoting an aggressive phenotype." (PMID 22469146, 2012). "Consequently, TRI-BE has important inhibitory effects on the biological activity of PC3 prostate tumor cells that were demonstrated in the migration and cell invasion assays, along with a decrease in MMP-9 segregation, which led to a decrease in the progression of metastasis in PC3 tumor cells." (PMID 37299000, 2023). "Another prior study has shown that TNF-α directly and/or indirectly induces proteases such as MT1-MMP and MMP9, and also promotes CCR7 upregulation, thereby contributing to cancer cell migration from breast and prostate tumors." (PMID 33816268, 2021). "On the other hand, in a mast cell-infiltrated prostate tumor region, the HOTAIR-polycomb repressive complex supresses AR transcription, consequentely promoting cell invasion with increased matrix metalloproteinase-9 (MMP9) expression." (PMID 26690121, 2015). "Prostate tumours, in particular, express increasing amounts of MMP2 and MMP9 as they progress to higher-grade tumours and greater degrees of metastatic potential." (PMID 18182993, 2008). "The present results highlight the potential value of MMP-2 and MMP-9 expression for predicting the behavior of prostate tumors after prostatectomy with both positive and negative surgical margins." (PMID 25097794, 2014). "Moreover, the prostate tumours had high levels of gelatinase (MMP2 and MMP9) expression and activity." (PMID 18182993, 2008).
Cirrhosis (23 papers, 2011 to 2026). A chronic disorder of the liver in which liver tissue becomes scarred and is partially replaced by regenerative nodules and fibrotic tissue resulting in loss of liver function. "In conclusion, MMP‐9 inhibition or deletion ameliorated the severity of cirrhosis, portal hypertension, and associated derangements." (PMID 34647412, 2021). "On the other hand, the other 3 markers (SOD, NF-κB, and MMP9) were statistically significant discriminators of HCC from cirrhosis at cutoff values of ≤−810.8, ≤ 197, and > 166.8, respectively." (PMID 41326479, 2025). "The elevated MMP9 expression in HCC compared to HCV-related cirrhosis underscores its role in extracellular matrix remodeling and tumor invasion, while the significant decline in SOD highlights increasing oxidative imbalance during malignant transformation." (PMID 41326479, 2025). "Our study also explored the role of SOD, MMP9, and NF-κB as diagnostic differentiators between HCV-related cirrhosis and HCC." (PMID 41326479, 2025). "MMP9 exhibited the highest diagnostic performance of the five measured biomarkers, discriminating against HCC vs. HCV-related cirrhosis with specificity and sensitivity of 100% and 90%, respectively, at a cut-off value > 166.8." (PMID 41326479, 2025). "A recent study discovered that the expression levels of FABP4 and MMP9 can effectively identify patients who are at risk of progressing from MAFLD to MASH, as well as those at risk of advancing from MASH to cirrhosis and HCC, respectively." (PMID 40435176, 2025). "After erlotinib treatment, expression of antifibrotic pathways, including Mmp2, Mmp3, and Mmp8, were enhanced in PCLS from CDAHFD-induced cirrhosis, while expression of profibrotic pathways, including Mmp9 and Mmp13, were hampered." (PMID 39445861, 2024). "Studies have shown that abnormal accumulation of collagen in the liver and progression of NAFLD to NASH and cirrhosis increase MMP-9 serum levels." (PMID 34479550, 2021). "We identified two genes, fatty acid binding protein-4 (FABP4) and matrix metalloproteinase-9 (MMP9), which respectively allowed distinguishing patients at risk of progression from NAFL to NASH and from NASH to cirrhosis and HCC." (PMID 31874999, 2019). "The next step will be to use MMP-9 knockout mice in analyses of treatment for cirrhosis-induced lung injury." (PMID 24733017, 2014). "In the presence of increased mmp-9 mRNAexpression, the fibrosis to cirrhosis transition occurred." (PMID 37538808, 2023). "In addition, MSCs can also alleviate cirrhosis through expressing matrix metalloproteinase-9 (MMP-9), which has antifibrotic effect through degrading the extracellular matrix." (PMID 25861263, 2015). "Therefore, we sought to determine expression of the rat genes Mmp2, Mmp9, Timp1 and Timp2 in the liver of CCl4-treated rats with different degrees of cirrhosis." (PMID 21813019, 2011). "Therefore, our data showed that MMP9 hepatic mRNA levels could be used earlier as a prognostic marker to identify NASH patients whose disease could progress to cirrhosis and HCC." (PMID 31874999, 2019). "Thus, high MMP9 expression levels could be associated with the progression from steatosis to NASH and possibly with the progression from NASH to HCC or cirrhosis." (PMID 31874999, 2019). "Specifically, by using ascites from small patient groups with HGSOC or cirrhosis and a small set of cancer-associated proteins, we observed that EV-associated MMP9 in HGSOC is predominantly localized in AV-binding EVs and that both CD59 and MMP9 in AV-binding EVs are candidate biomarkers for HGSOC." (PMID 28607529, 2017). "The relative expression of MMP9, NF-κB, and SOD concentration also displayed a significant increase in HCV-related cirrhosis patients compared to the control group." (PMID 41326479, 2025).
Cirrhosis (continued). "QuantSeq 3′ mRNA sequencing revealed thirty-three downregulated genes associated with ECM after the NK cell treatment of CCl4-induced cirrhosis, including six MMP genes (MMP3, MMP8, MMP9, MMP11, MMP12, and MMP14)." (PMID 37189708, 2023). "In established end-stage injury with cirrhosis there is increased expression of MMP-2, MMP-9, MMP-14 as well as TIMP-1 and TIMP-2." (PMID 25076423, 2014). "Moreover, MMP-9 is produced in CCl4-induced liver injury after a single injection and in hepatitis C virus-induced cirrhosis; however, its activity was not related to the degree of fibrosis." (PMID 27776513, 2016).